SERPINA1 (serpin family A member 1)
Diseases named in the same sentence as SERPINA1 in open-access papers (continued):
Sharing a sentence is not in itself a finding about the gene and the disease.
lymph node metastasis (7 papers, 2015 to 2025). "Some studies have shown that increased expression of SERPINA1 is associated with advanced disease, lymph node metastasis, and poor prognosis." (PMID 41425595, 2025). "Taken together, these results showed that Snail and serpinA1 were associated with advanced clinical stage, lymph node metastasis, and poor prognosis in patients with CRC." (PMID 26015410, 2015). "High expression of SERPINA1 has been associated with advanced stage, lymph node metastasis, and poor prognosis of CRC patients, and may be useful as a prognostic marker and candidate therapeutic target for CRC." (PMID 33126898, 2020). "Next, we explored the potential association of plasma levels of fuco-SERPINA1, SERPINA1 and CA19-9 with different clinicopathological characteristics (gender, age, TNM stage, tumor stage, lymph node metastasis and distant metastasis) of enrolled PC patients." (PMID 34199928, 2021). "SerpinA1 was also frequently overexpressed in patients with advanced stages (P = 0.014) and lymph node metastasis (P = 0.006)." (PMID 26015410, 2015). "Consistent with this, we found that serpinA1 was significantly correlated with stage and lymph node metastasis in CRC." (PMID 26015410, 2015). "Finally, we performed a LASSO logistic regression analysis of the gene expression matrix of seven of the THCA cohort from the TCGA database by the presence or absence of lymph node metastasis to finalize the risk scores constructed for the five most relevant genes (EVA1A, SERPINA1, FN1, TNC, MXRA8)." (PMID 35141140, 2021).
pancreatitis (7 papers, 2007 to 2022). Inflammation of the pancreas. "The ratio of PRSS1 and its inhibitor SERPINA1 or alpha-1-antitrypsin is elevated in patients with PDAC, and SERPINA1 deficiency is associated with pancreatitis and cachexia phenotypes." (PMID 33334063, 2020).
primary ciliary dyskinesia (7 papers, 2016 to 2024). A rare, genetically heterogeneous, primarily respiratory disorder characterized by chronic upper and lower respiratory tract disease. "Here, we report on a patient with Kartagener's syndrome who was diagnosed with AAT genotype deficiency and had a previously unidentified heterozygous variant rs1460874866 in the exon 4 (NM_001127701.1) of the SERPINA1 gene." (PMID 39492455, 2024). "As it is recommended that all patients with Kartagener’s syndrome are tested for AATD, the patient was referred for SERPINA1 genotyping." (PMID 39492455, 2024).
cervical carcinoma (6 papers, 2009 to 2025). A carcinoma arising from either the exocervical squamous epithelium or the endocervical glandular epithelium. "The results showed that except for SERPINA1, the other five genes were down-regulated in cervical cancer(all P < 0.05)." (PMID 34238288, 2021). "Colocalization and possible interactions of SERPINA1 and SERPINA3 have been reported in patients with immunological renal disease, in brain tissues of Alzheimer’s patients, or in patient-derived HLA-positive cervical carcinoma." (PMID 38909263, 2024). "Finally, among the 12 autophagy biomarkers related to the survival of cervical cancer, based on literature search, we selected 6 genes (ATG4C, ATG4D, CD46, TP73, SERPINA1 and HSPB8) to verify their RNA expression in CC and normal cervical tissue samples." (PMID 34238288, 2021).
dementia (6 papers, 2012 to 2023). Loss of intellectual abilities interfering with an individual's social and occupational functions. "Our results indicate that PD patients in whom the level of the most acidic serpinA1 isoform is higher than this 2nd cut-off value have a 6.4 fold increased chance to be associated with dementia." (PMID 27184740, 2016). "We found that patients with a positive serpinA1 test have a more than 6 times higher risk of an association with dementia." (PMID 27184740, 2016). "As an example, the development of dementia in PD was linked to hypersialylated serpinA1." (PMID 35805926, 2022). "PD patients who have a higher normalized serpinA1 signal of the most acidic isoform (peak 0) than the selected 2nd cut-off value of 6.44 * 10−3 have a 6.4 fold higher risk to be associated with dementia compared to PD patients with a normalized serpinA1 signal below this cut-off." (PMID 27184740, 2016). "The detection of more than five charge isoforms of serpinA1 in PDD patients compared to PD patients and controls confirms serpinA1 to represent a potential marker for the diagnosis of dementia in PD patients." (PMID 27184740, 2016). "The measurement of serpinA1 can therefore support the early clinical diagnosis of dementia in PD patients and help to stratify patient populations for therapeutic trials." (PMID 27184740, 2016). "Secondly, we focused on AD patients in different disease stages, namely mild cognitive impairment (AD-MCI) and dementia (AD-dem), in order to evaluate whether serpinA1 expression differs along the clinical continuum." (PMID 35805926, 2022). "Confirming our previous results that isoform 0 might be selectively involved in the development of dementia due to LBD, analysis of serpinA1 isoforms might represent an interesting diagnostic supplement, especially for patients with neurodegenerative dementias." (PMID 35805926, 2022). "Moreover, the CSF serpinA1 isoform analysis might already predict cognitive impairment in PD patients who will develop a dementia in the course of the disease." (PMID 27184740, 2016). "Analysis of serpinA1 isoform provided good di-agnostic accuracy in discriminating AD patients versus controls (AUC = 0.80) and versus LBD patients (AUC = 0.92), with best results in patients in the dementia stage (AUC = 0.97)." (PMID 35805926, 2022). "Other proteins associated with HDLs that could be relevant to HDL metabolism and/or dementia include apolipoprotein C-I, paraoxonase 1 (PON1), and serpin family A member 1 (SERPINA1)." (PMID 30487733, 2018). "Modified serpinA1 in cerebrospinal fluid (CSF) was suggested as an early biomarker for differentiation between Parkinson patients with (PDD) or without dementia (PD)." (PMID 27184740, 2016). "We speculate that the CSF serpinA1 isoform analysis by the novel CIEF-immunoassay may turn out to have value for the biomarker supported prediction of cognitive impairment, as the serpinA1 isoform pattern might already be altered at a pre-dementia stage in PD patients who will develop PDD." (PMID 27184740, 2016).
fibrosis (6 papers, 2009 to 2024). the formation of excess fibrous connective tissue in an organ or tissue in a reparative or reactive process. "To determine whether these results were specific to NASH-fibrosis or were more generally reflective of hepatocyte dysfunction, we compared associations from the five NASH-fibrosis variants with SNP-metabolite associations for HFE and SERPINA1 variants." (PMID 32720691, 2020).
hepatitis C (6 papers, 2014 to 2024). "Chart review of the seven individuals who were heterozygous for a single pathogenic allele in SERPINA1 and had a history of hepatitis C infection revealed normal A1A levels in the two individuals in whom levels were measured." (PMID 37651384, 2023). "None of the seven individuals who were both heterozygous for either the S or Z allele and had a history of hepatitis C infection had a second pathogenic variant in SERPINA1 identified in sequencing." (PMID 37651384, 2023). "We sought to compare the risk of liver transplantation associated with hepatitis C infection with AATD heterozygotes and homozygotes and determine if SERPINA1 sequencing would identify undiagnosed AATD." (PMID 37651384, 2023). "The remaining 133 individuals did not have evidence of hepatitis C infection, and SERPINA1 sequencing revealed six individuals with a second variant of possible clinical significance." (PMID 37651384, 2023). "Genotypes, exposures, and phenotypes of individuals who had undergone liver transplant and were either found to be compound heterozygous for pathogenic variants in SERPINA1 (individuals 1–6) or were carriers for AATD and had hepatitis C infection (individuals 7–13)." (PMID 37651384, 2023).
liver dysfunction (6 papers, 2020 to 2025). "Importantly, these subjects are asymptomatic, making them an ideal group to study as they do not present with the liver dysfunction associated with symptomatic AAT deficiency in those with homozygous SERPINA1 mutations." (PMID 39788946, 2025).
frontotemporal lobar degeneration (5 papers, 2019 to 2025). "Indeed, pSAD-based minigenes have constituted an invaluable technology to functionally test variants of other disease genes such as GRN (Frontotemporal Dementia), SERPINA1 (Severe alpha-1 antitrypsin deficiency) and CHD7 (Charge Syndrome) genes." (PMID 31191615, 2019). "Serpina1 upregulation has been reported in brain and CSF of subjects with Creutzfeldt-Jakob disease (CJD) and frontotemporal lobar degeneration (FTLD)." (PMID 40779003, 2025). "The increased level of SERPINA1 was also observed in Creutzfeldt–Jakob disease (CJD) and frontotemporal lobar degeneration (FTLD)." (PMID 37238921, 2023). "Recently, it has been shown that another member of the serpin superfamily, SERPINA1, is not expressed at high levels in normal brain tissue, but it is overexpressed in AD, frontotemporal lobar degeneration, and CJD, suggesting that its expression may be detrimental for neuronal function." (PMID 35416570, 2022).
metastatic disease (5 papers, 2018 to 2026). "SERPINA1 expression increased progressively from normal skin to nevi and metastatic melanoma, yet higher intratumoral levels correlated with improved overall survival in metastatic disease." (PMID 41594664, 2026).
periodontitis (5 papers, 2013 to 2025). An acute or chronic inflammatory process that affects the tissues that surround and support the teeth. "Lastly, further studies are required to determine the location of SERPINA1, ERLEC1, and VWF in ERS and investigate the mechanisms by which these three genes are linked to periodontitis." (PMID 36072904, 2022). "Through machine learning, we identified three potential biomarkers of periodontitis, SERPINA1, ERLEC1, and VWF and found strong correlations between these ERS-related genes and immune cell infiltration." (PMID 36072904, 2022). "SERPINA1, ERLEC1, and VWF showed high diagnostic values (AUC > 0.85), so they were considered as potential biomarkers for periodontitis." (PMID 36072904, 2022). "In order to resist the tissue damage caused by tissue-destructive enzymes and reactive oxygen species (ROS) in periodontitis, a series of anti-inflammatory mediators were produced in response by cells; this could explain the increase of SERPINA1 in the diseased samples of our study." (PMID 36072904, 2022). "After further screening by the validation set, SERPINA1, ERLEC1, and VWF were selected as potential biomarkers of periodontitis." (PMID 36072904, 2022). "Three ERS-related genes, SERPINA1, ERLEC1, and VWF, showed valuable biomarker potential for periodontitis, which provide a target base for future studies on early diagnosis and treatment of periodontitis." (PMID 36072904, 2022). "Therefore, SERPINA1, ERLEC1, and VWF were selected as potential biomarkers of periodontitis." (PMID 36072904, 2022). "In our study, SERPINA1 was the core gene in PPI and correlated with seven ERS-related genes including ERLEC1, VWF, EDEM2, DERL3, APOE, IL6, and CXCL8, suggesting that SERPINA1 may play an essential role in the pathological process of periodontitis." (PMID 36072904, 2022).
pneumothorax (5 papers, 2020 to 2025). Abnormal presence of air in the pleural cavity. "This study aimed to determine the frequency and distribution of SERPINA1 gene mutations in individuals diagnosed with SP and to assess the distribution of these mutations according to pneumothorax type - primary SP (PSP) versus SSP." (PMID 41054037, 2025).
sickle cell disease (5 papers, 2015 to 2021). Sickle cell anemias are chronic hemolytic diseases that may induce three types of acute accidents: severe anemia, severe bacterial infections, and ischemic vasoocclusive accidents (VOA) caused by sickle-shaped red blood cells obstructing small blood vessels and capillaries. "Recent study have suggested an association between SERPINA1 gene polymorphism, levels of AAT and sickle cell disease." (PMID 29719508, 2018).
AIDS (4 papers, 2009 to 2025). A syndrome resulting from the acquired deficiency of cellular immunity caused by the human immunodeficiency virus (HIV). "The analysis of a clinical case indicates that individuals with pre-existing SERPINA1 deficiency experience faster progression of HIV/AIDS, implying that SERPINA1 may function as an endogenous suppressor of the disease." (PMID 41226631, 2025).
bacteremia (4 papers, 2013 to 2024). "Some of the hemostasis genes that we identified as candidaemia susceptibility genes (SERPINA1, LAT and F5) have also been shown to be important for bacterial sepsis." (PMID 28727728, 2017).
endometriosis (4 papers, 2022 to 2025). The growth of functional endometrial tissue in anatomic sites outside the uterine body. "Furthermore, our findings indicate that the suppression of SERPINA1 expression in eutopic endometrial stromal cells significantly upregulates inflammatory cytokines linked to endometriosis." (PMID 40802848, 2025). "We have previously observed reduced expression of the anti‐inflammatory factor SERPINA1 in endometriosis‐like lesions in a mouse model implanted with human ESCs." (PMID 40802848, 2025). "In this model, levels of interleukin 6 (IL6) and prostaglandin E2 (PGE2) were elevated, while levels of the serine protease inhibitor SERPINA1 were reduced in endometriosis‐like lesions." (PMID 40802848, 2025). "The present study is the first to demonstrate that SERPINA1 expression is significantly reduced in ectopic compared to eutopic endometrium in patients with endometriosis." (PMID 40802848, 2025). "Previously, we found decreased SERPINA1 (alpha-1 antitrypsin) expression in endometriosis-like lesions in a mouse model of endometriosis, suggesting that it exacerbated inflammation in these lesions." (PMID 36093086, 2022). "Because expression of SERPINA1 is decreased in endometriosis-like lesions in a mouse model, it is possible that TLRs may be involved in inflammatory responses in these lesions." (PMID 36093086, 2022). "Previous studies showed that a reduction in intracellular SERPINA1 protein levels exacerbates inflammatory responses in endometriosis-like lesions in mice, and increases endoplasmic reticulum stress-induced cytokine production by cultured human adipocytes and trophoblasts." (PMID 36093086, 2022). "However, it remains unclear whether the reduction of SERPINA1, in combination with PGE2 and thrombin, synergistically influences the expression of inflammatory factors in endometriosis lesions and the underlying mechanisms." (PMID 40802848, 2025). "Next, topological analysis using the cytoHubba plugin in Cytoscape identified MMP7, MMP11, SERPINA1, THBS1, and IGFBP5 as candidate hub genes expressed in both adenomyosis and endometriosis." (PMID 41272701, 2025). "In endometriosis-like lesions, levels of interleukin 6 (IL-6) and prostaglandin E2 (PGE2) increased, whereas that of SERPINA1 (known as alpha-1 antitrypsin) decreased." (PMID 36093086, 2022). "However, SERPINA1 and THBS1 were found to be significantly downregulated in these women relative to endometriosis." (PMID 41272701, 2025). "However, the intricate molecular mechanisms by which SERPINA1, PGE2, and thrombin influence the expression of inflammatory factors associated with the development of endometriosis lesions are not fully elucidated." (PMID 40802848, 2025).
glomerulonephritis (4 papers, 2017 to 2024). A renal disorder characterized by damage in the glomeruli. "A recent study showed high amount of SERPINA1 in the urine of patients with glomerulonephritis could differentiate MCD and FSGS." (PMID 28522940, 2017).
heart failure (4 papers, 2014 to 2025). Inability of the heart to pump blood at an adequate rate to meet tissue metabolic requirements. "Consistent with our result, a weighted gene co-expression network analysis research showed that the SERPINA1 was identified and validated for the predictive value in identifying future heart failure after AMI50." (PMID 39893248, 2025). "Serpina1 upregulation is associated with multiple CVDs, including heart failure, and levels were lower in non-ischemic right ventricles (RV) than in ischemic RVs." (PMID 29029392, 2017).
osteoarthritis (4 papers, 2021 to 2025). A noninflammatory degenerative joint disease occurring chiefly in older persons, characterized by degeneration of the articular cartilage, hypertrophy of bone at the margins and changes in the synovial membrane. "High aldehyde dehydrogenase (ALDH) activity has been reported in osteoarthritis patients’ chondrocytes and elevation of Serpina1 was also observed in the joint homogenates of the AIA group." (PMID 35433699, 2022).
osteosarcoma (4 papers, 2020 to 2025). A usually aggressive malignant bone-forming mesenchymal neoplasm, predominantly affecting adolescents and young adults. "However, the diagnostic and prognostic roles of SERPINA1 in osteosarcoma were still obscure." (PMID 32974202, 2020). "In the Xiantao database, higher SERPINA1 expression was connected to better overall survival (OS) in BRCA (breast invasive carcinoma), COAD (colon adenocarcinoma), DLBC, KIRC, KIRP, osteosarcoma, SARC (sarcoma), and SKCM (skin cutaneous melanoma)." (PMID 37511325, 2023).
Parkinson disease (4 papers, 2016 to 2025). A progressive degenerative disorder of the central nervous system characterized by loss of dopamine producing neurons in the substantia nigra and the presence of Lewy bodies in the substantia nigra and locus coeruleus. "Here we report on the development of a new capillary isoelectric focusing immunoassay (CIEF-immunoassay) for the analysis of serpinA1 charge isoforms in CSF and its ability to differentiate between cognitive normal and demented Parkinson patients." (PMID 27184740, 2016). "The GSEA results suggest that ENTPD1, SERPINA1, and TACSTD2 may be involved in the occurrence and development of PTC by jointly regulating the spliceosome, Parkinson’s disease, and cytokine–cytokine receptor interaction pathways." (PMID 40520228, 2025).
Allergy (3 papers, 2022 to 2024). An allergy is an immune response or reaction to substances that are usually not harmful. "For adverse effect identification, the MR-PheWAS suggested that increased level of SERPINA1 increased systolic and diastolic blood pressure level; and inhibition of ICAM1 increased the risk of irritability, allergy, and nervous feelings." (PMID 35772218, 2022).
ANCA-associated vasculitis (3 papers, 2024). "•SERPINA1 gene polymorphisms are associated with ANCA-associated vasculitis." (PMID 39476516, 2024). "While numerous studies have established a connection between Single Nucleotide Polymorphisms (SNPs) in the SERPINA1 gene and ANCA-Associated Vasculitis (AAV), limited research has delved into the impact of these polymorphisms on the prognosis of these patients." (PMID 39476516, 2024).
aortic aneurysm (3 papers, 2017 to 2024). A ruptured aneurysm located in the wall of the proximal portion of the descending aorta proceeding from the arch of the aorta. "HMGA1 has been found associated with the development of aortic aneurysm and dissection (AAD) via transcriptome-wide association study (TWAS) analysis and SERPINA1 has been identified as a reliable molecular marker for the early diagnosis of AD patients." (PMID 37877967, 2023).